IL13 (interleukin 13)
Diseases named in the same sentence as IL13 in open-access papers (continued):
Sharing a sentence is not in itself a finding about the gene and the disease.
asthma (continued). "As we know, this is the first systematic review assessing efficacy and safety of anti-IL-13 monoclonal antibodies for uncontrolled asthma." (PMID 30703143, 2019). "IL-5 is a critical mediator of eosinophil activation to promote bronchial inflammation and asthma symptoms, and IL-13 is involved in bronchial hyperreactivity and airway remodeling, such as mucus metaplasia and subepithelial fibrosis." (PMID 31861989, 2019). "Overexpression of pulmonary IL-13 in transgenic mice led to development of features typical of asthma, such as eosinophilic airway inflammation, increased mucus production, sub-epithelial fibrosis and airway hyper-responsiveness." (PMID 31315668, 2019). "Currently, dupilumab is the only available biologic drug targeting both IL-4 and IL-13, approved to treat patients with moderate-to-severe asthma and airway or peripheral eosinophilia." (PMID 31355170, 2019). "Many studies revealed that IL-13 is the major effector for perturbation of TJ permeability in Th2-high asthma patients." (PMID 31262043, 2019). "Interleukin-13 (IL-13) drives symptoms in asthma with high levels of T-helper type 2 cells (Th2-cells)." (PMID 31262043, 2019). "While interleukin 13 is considered as inflammatory promoting, Interleukin 10 has an anti-inflammatory effect and has a low level in patient with asthma and COPD." (PMID 31363402, 2019). "In rat models with asthma, the treatment of NM showed a decreased eosinophil and neutrophil infiltration, and decreased levels of inflammatory factors such as IL-5, IL-6, IL-13, and IL-17 in bronchoalveolar lavage fluid." (PMID 31552177, 2019). "Emerging evidence indicates that the IL-13 and IL-17 pathways are reciprocally regulated in asthma, and each contributes to the activation and recruitment of different granulocytic populations in the airway." (PMID 30616547, 2019). "Recently, therapies targeting IL-4, IL-5, and IL-13 have shown potential efficacy for treating asthma." (PMID 31114590, 2019). "IL-4, IL-5, and IL-13, while important for promoting the clearance of parasites, can promote a disease state when improperly expressed, such as with asthma and allergy, by activating immune cells involved in these pathologies." (PMID 30630412, 2019). "The anti-IL-4Rα antibody is directed against IL-4Rα and blocks the IL-4 and IL-13 pathways; this asthma treatment is under development." (PMID 31284537, 2019). "The relevance of IL-13 in asthma pathophysiology via DNA methylation has also been evidenced in a transgenic mouse model where expression of IL13 is induced." (PMID 31731604, 2019). "More and more clinical trials have tried to assess the clinical benefit of anti-interleukin (IL)-13 monoclonal antibodies for uncontrolled asthma." (PMID 30703143, 2019). "Similar to 6A4G7, 17A1D10 inhibited D. pteronyssinus or Der p 2-stimulated IL-5 and IL-13 production in the MoDC/CD14− PBMC co-cultures of patients with asthma (respectively)." (PMID 31861989, 2019). "Our meta-analysis investigated the potential of anti-IL-13 to be an addition on current asthma controller therapies in patients with uncontrolled asthma." (PMID 30703143, 2019). "Inhibition of interleukin (IL)-13, a Type 2 inflammatory mediator in asthma, improves lung function and reduces exacerbations; however, more effective therapies are needed." (PMID 30616547, 2019). "We also found that NIP45 deficiency led to a significant decrease of the Th2 cytokines IL-4, IL-5 and IL-13, which are the principle components in the onset of asthma." (PMID 31666531, 2019). "Increased polarization and activation of M2 macrophages, which was induced by interleukin (IL)-4 and IL-13, are found in asthma and are suggested to be involved in asthma pathogenesis." (PMID 31547356, 2019). "The aim of this study is to evaluate the efficacy and safety of anti-IL-13 monoclonal antibodies for uncontrolled asthma." (PMID 30703143, 2019).
asthma (continued). "There is an obvious reason for the weak efficacy of asthma therapies targeting IL-4 and IL-13 since both cytokines share the same signaling pathway." (PMID 31216735, 2019). "Inhibition of the Th2 cytokine IL-13 with an anti-IL-13 mAb has been shown to inhibit airway remodeling in a chronic mouse model of asthma." (PMID 31649532, 2019). "Current biologic treatments for severe asthma target a type 2-driven eosinophilic phenotype by blockade of IgE, IL-4Rα, IL-13, and, importantly, IL-5/IL-5Rα." (PMID 31415658, 2019). "Further research is thus warranted to compare IL-5 and IL-13 production in the same population before and after asthma treatment." (PMID 31861989, 2019). "It has since been shown that Th2 cells play a central role in the pathogenesis of asthma by secreting typical Th2 cytokines, such as interleukin (IL)-4, IL-5, and IL-13." (PMID 31216735, 2019). "Type 2 cytokines such as IL-4, IL-5, and IL-13 play a critical role in mucous cell metaplasia and mucus hypersecretion during asthma." (PMID 30654796, 2019). "In fact, type II innate lymphoid cells (ILC2) are known to produce IL-13 and to play a role in experimental and clinical asthma pathology." (PMID 30761137, 2019). "The importance of type 2 immune responses, characterized by the production of interleukin-4 (IL-4), IL-5, and IL-13, has received much attention in the pathogenesis of asthma." (PMID 31114590, 2019). "These negative clinical results contrast with positive findings from blocking IL-13 signaling in experimental models of asthma, raising doubts about the transferrable value of some models." (PMID 31866859, 2019). "IL-4 aids in directing naïve CD4+ Th cells towards a Th2 phenotype, while IL-13 enhances airway inflammation and remodeling; dupilumab has dual inhibition of both IL-4 and IL-13 which demonstrates more beneficial effects in asthma therapy." (PMID 31728232, 2019). "More recently biologic therapies that target T2 pathways including IL-4, IL-13, and IL-5 have been shown to be effective in patients with asthma and nasal polyps." (PMID 31294006, 2019). "Testing and analysis for total IgE, aeroallergen-specific IgE antibodies, serum cytokines IL-4, IL-13, IL-10, and IFN-γ levels, and total peripheral eosinophilic index were used as immunological biomarkers known to be associated with asthma." (PMID 31336954, 2019). "The tissues used to represent airway inflammation in this study were nasal epithelial cells re-stimulated with IL-13 compared to nasal brushes of patients with asthma." (PMID 31824894, 2019). "In vivo IL-13 neutralization also resulted in lower collagen deposition in lung of mice subjected to experimental asthma." (PMID 31805682, 2019). "The humanized anti-IL-13 antibody lebrikizumab improved lung function and the rate of asthma exacerbations in patients with moderate to severe asthma." (PMID 31284537, 2019). "We previously reported higher IL-19 expression in asthma patients and that patients with high IL-19 expression also have high IL-4 and IL-13 expression." (PMID 31114590, 2019). "Interleukin (IL)-13 is a type-2 pleiotropic cytokine thought to play a central role in asthma pathophysiology." (PMID 31315668, 2019). "In the dexa/hypergravity group, IL-4, IL-5 and IL-13 secretion in the BAL fluid decreased statistically significantly (p < 0.001) compared with the asthma group." (PMID 29772010, 2018). "IL-13 is a prominent mediator of allergic lung disease, including pulmonary inflammation, asthma and anaphylaxis." (PMID 30460209, 2018). "We showed associations with known asthma loci in IL1RL1, IL13, LINC01149, near GSDMB, and in the C11orf30-LRRC32 region." (PMID 30373671, 2018). "The adoptive transfer of IL-4- and IL-13-producing iNKT cells restored the asthma severity, demonstrating that iNKT cells favored allergic asthma symptoms through the production of these cytokines." (PMID 30105031, 2018).
asthma (continued). "M2 macrophages are characterized by the increased expression of IL-4 and IL-13, which are very crucial cytokines in asthma pathogenesis." (PMID 29316647, 2018). "A number of prior GWAS have identified distinct genetic susceptibility for pediatric onset asthma, particularly implicating ORLDM3/GSDMB, IL1RL1, and IL13, which were all found to have association with childhood asthma in the current analysis." (PMID 30373671, 2018). "Many clinical trials have revealed that antibodies against IL-5 or IL-5 receptor, IL-13, and IL-4Rα modestly reduced asthma exacerbations and improved lung function." (PMID 30050954, 2018). "Several anti-IL13 drugs are now available for human use and are ready for being tested in clinical trials on asthma and atopic dermatitis in clinical trials." (PMID 29942802, 2018). "Another feature of asthma in mice and humans, to be addressed and thought about in future studies, in relevance to IL-13 in March1 KO mice in this model is subepithelial lung fibrosis." (PMID 29854835, 2018). "Recent studies also report positive findings on the efficacy of new therapies targeting cytokines interleukin IL-13 and IL-4 in asthma and atopic dermatitis." (PMID 29771307, 2018). "Of note, high levels of IL13 characterize patients with asthma and with atopic dermatitis, two very frequent conditions never associated with proteinuria." (PMID 29942802, 2018). "For example, in a lebrikizumab (an anti-IL-13 mAb) dose-finding study in moderate-to-severe asthma patients with high periostin levels, there was a direct correlation between exacerbation rate and lebrikizumab dose." (PMID 29879991, 2018). "Intratracheal administration of IL-13 to BALB/c mice resulted in an asthma phenotype in-vivo showing, for example, elevated levels of eosinophils and AHR 48 h after cytokine administration." (PMID 30500834, 2018). "Mice deficient for IL-4, IL-13, or STAT6 develop attenuation of certain features of asthma, including eosinophil recruitment and airway hyperresponsiveness." (PMID 30147700, 2018). "IL-13 is considered one of the key cytokines in the asthma pathogenesis, however, the effect of IL-13 was mostly studied in rodents." (PMID 30500834, 2018). "The reduction or blocking of IL-13-mediated pathological effects can be beneficial for asthma patients." (PMID 30500834, 2018). "Woodruff and coworkers identified the two most popular asthma subgroups, “T2-high” and “T2-low,” through the different expression of IL-5 and IL-13 transcripts in bronchial biopsies." (PMID 29992143, 2018). "Due to its ability to activate Th2 and dendritic cells, IL-33 plays an important role in initiating allergic inflammation and asthma by producing Th2 cytokines including IL-5 and IL-13." (PMID 29540228, 2018). "Previous studies have shown that the severity of inflammatory responses markedly decreased in MMP9−/− asthma mouse models, and IL-13-induced inflammation reduced upon MMP12 knockdown in mice." (PMID 30250465, 2018). "Th2-type CD4+ T cells secrete IL-4, IL-5, and IL-13, which play important downstream roles in asthma pathogenesis." (PMID 29507584, 2018). "A study of experimental RV infection in asthma showed that virus-induced IL-33 release correlated with high IL-5 and IL-13 concentrations in the airway." (PMID 30174671, 2018). "The present study also showed that resveratrol treatment significantly reduced the levels of Th-2 cells and Th2-related cytokines (IL-5, and IL-13) in addition to asthma-related cytokines such as TGF-β in BALF, and serum." (PMID 30619345, 2018). "Mast cells also contribute to the secretion of proinflammatory cytokines such as TNF-α and IL-13 which drive the innate and adaptive immune responses in asthma." (PMID 29854739, 2018). "This was not replicated in MAAS3, but previous work in MAAS had identified that a strong PBMC Th2 response (IL-5, IL-13) to HDM stimulation at age 8 was associated with increased risk of HDM sensitisation and asthma." (PMID 30320550, 2018).
asthma (continued). "As IL-13 was shown to be critical in asthma pathogenesis, it is an attractive target for pharmacological intervention." (PMID 30500834, 2018). "As a downstream molecule of IL-4 and IL-13, it has been proposed as an important biomarker of the Th2-high eosinophilic phenotype of asthma." (PMID 29580282, 2018). "The upregulation of IL-13 transcripts in BAL cells of patients with mild asthma after low-dose allergen challenged is consistent with its higher expression level of IL-13 mRNA in bronchial mucosa." (PMID 29991953, 2018). "Inflammatory cytokines such as IL-13 and TNF-α, which are implicated in asthma, augment CD38 expression and cADPR-mediated Ca2+ release and increase contractility of ASM." (PMID 29576747, 2018). "Many other pathways were also identified that are regulated by IL-13 and relevant to asthma pathogenesis (e.g. CCL17, CCL26, CTGF, FCER1A, KITLG, MUC2, NOS2, TLR3)." (PMID 29367592, 2018). "In asthma, Type-2 inflammatory cytokines IL-4 and IL-13 induce upregulation of the POSTN gene responsible for the encoding of periostin." (PMID 30065761, 2018). "IL-13-directed treatment showed the efficacy in the maintenance of asthma control when corticosteroid dose was reduced in patients with moderate to severe asthma." (PMID 29951106, 2018). "As a Th2-driven inflammatory response, asthma is characterized by increase in the levels of IL-4, IL-5, IL-13, and GM-CSF along with an increase in the level of TNF-α and TGF-β in BALF and serum, which primarily act as pro-inflammatory cytokines." (PMID 30619345, 2018). "IL-13 has been shown to play a role in mucus metaplasia and administration of anti-IL-13 neutralizing antibody can reduce the asthma-like phenotype following early-life HRV infection." (PMID 30513770, 2018). "IL-13 can also enhance survival of eosinophils and contribute to the pathological activities of these cells in asthma." (PMID 29991953, 2018). "Immune and epithelial cells of the lung can respond to inhaled substances by the release of central mediators of asthma, such as IL-4 and IL-13, as well as inflammatory mediators, such as IL-1β, and immune cell attracting proteins, such as Mcp-1." (PMID 29614747, 2018). "Mice overexpressing IL-13 replicate several features of asthma, including pulmonary eosinophilia, epithelial hyperplasia, airways obstruction, and hyperresponse to cholinergic." (PMID 29991953, 2018). "Inflammatory cytokines like interleukin-4 (IL-4), IL-5, and IL-13 are also increased and altered along with asthma exacerbation." (PMID 30170608, 2018). "IL-4 and IL-13 are involved in the production of IgE and the pathogenesis of several aspects of bronchial inflammation in asthma." (PMID 29879991, 2018). "IL-13 is considered to be a central molecule in asthma which can directly induce pathomechanisms leading to the disease development." (PMID 30500834, 2018). "In mild and moderate asthma, the T helper type 2 (Th2) cells dominated over the T cell lineage in the airway, which were the producers of the typeII cytokines IL4 and IL13, which had a high message and protein level in asthma patients." (PMID 29751569, 2018). "Initially IL-13 was a target for host directed therapy for asthma, dermatitis and other allergic diseases." (PMID 30460209, 2018). "Periostin is upregulated by IL-13 in bronchial epithelial cells and lung fibroblasts and deposited widely in the bronchi of subjects with asthma." (PMID 30048528, 2018). "TSLP also upregulates interleukin-13 (IL-13) production in natural killer T cells and decreases airway hyper-reactivity in an asthma model." (PMID 29670037, 2018). "In fact, ILC2 represents more than half of the IL-5- and IL-13-producing cells in the lungs of mice subjected to ovalbumin (OVA)- or house dust mite (HDM)-induced asthma." (PMID 29593738, 2018). "IL-13 is a key type 2 cytokine that orchestrates many of the features of airway inflammation and remodeling in human asthma." (PMID 29922162, 2018).
asthma (continued). "The location of the PCDH 1 is in 5q 31-33 chromosome which is the harboring zone for several genes like Interleukin-4 (IL-4), Interleukin-5 (IL-5), Interleukin-13 (IL-13), the candidate genes for asthma and allergy traits." (PMID 30510870, 2018). "IL-13 plays a central role in the pathogenesis of asthma by driving mucus production, airways hyper-responsiveness, and airways remodeling." (PMID 29367592, 2018). "In order to evaluate asthma-related biomarkers ex-vivo, the effects of IL-13 on eotaxin-3 and TARC secretion were measured in human PCLS in a dose-dependent manner." (PMID 30500834, 2018). "The results of present study showed that, although the concentrations of IL-5 and IL-13 were higher in asthmatic children with RV infection, it was not significantly different between mild, moderate, and severe acute asthma exacerbation." (PMID 30210646, 2018). "Both IL4 and IL13 were important in asthma pathology, typically in those patients with Th2 profile inflammation." (PMID 29751569, 2018). "Support for this mechanism came from studies using an AP-1 decoy molecule, which was used to block IL-4 and IL-13 production, and ameliorate disease symptoms in a model of asthma." (PMID 30459773, 2018). "In the pathogenesis of asthma, the Th2 and Th17 lymphocytes in the adaptive immune system can produce cytokines (such as IL-5, IL-13, and IL-17) to control disease." (PMID 30761008, 2018). "FA aggravates asthma, at least in part by increasing the T helper-2 dominant response, which is related to levels of the cytokine mediators of asthma (IL-4, IL-5, IL-9, and IL-13)." (PMID 29780828, 2018). "In people with asthma, IL-33 pre-exposure led to significantly higher RV-induced (in red) IL-5 and IL-13 release (in red) compared to RV alone (in green) (p = 0.02 and p = 0.003 respectively)." (PMID 30174671, 2018). "Type 2 cytokines, particularly IL-4 and IL-13, are important in the pathogenesis of human asthma and murine allergic airway disease, which is a useful, albeit imperfect, model of human asthma." (PMID 29182669, 2017). "In that regard, recent asthma treatments have been focusing on blocking Type 2 cytokines, notably IL-4, IL-5, and IL-13." (PMID 28848734, 2017). "Both IL-6 and IL-13 levels are usually elevated in asthma patients and are presumed to be closely correlated; we found that IL-6 levels were similar to IL-13 levels, supporting this idea." (PMID 29151835, 2017). "The IL-13 transcriptional signature can be used to identify individuals with type 2 high and type 2 low asthma; approximately 50% of people with asthma are type 2 high and exhibit worsened AHR to methacholine, higher serum IgE, and eosinophils." (PMID 29186064, 2017). "Promising results from clinical trials further support a key mechanistic role of IL-13 in asthma and other eosinophilic disorders." (PMID 29034234, 2017). "In asthma, Th2-related cytokines such as IL-4, IL-5, and IL-13 significantly increase; the development of antibodies against Th2-related cytokines is an active field of research." (PMID 29151835, 2017). "Heterogeneity in the severe asthma samples was evaluated using the IL-13 disease signature (CLCA1, SERPINB2 and POSTN) and the gene expression marker for steroid response (FKBP5)." (PMID 28045928, 2017). "Bioinformatics analysis determined complement base pairing with important cytokines as IL-13 and IL-23, both are recognized effectors in asthma pathway." (PMID 28886711, 2017). "Tralokinumab, a human IL-13-neutralizing monoclonal antibody blocking binding of IL-13 to both IL-13Rα1 and IL-13Rα2, has been assessed in clinical trials of moderate to severe uncontrolled asthma patients." (PMID 29034234, 2017). "In agreement with the in vitro experiments, we and others have demonstrated that pendrin is highly expressed in the lungs of asthma model mice such as ovalbumin-inhaled, IL-13-inhaled, and IL-13 transgenic mice." (PMID 29359006, 2017).